VRK3 (VRK serine/threonine kinase 3)
Description:
Plays a role in the regulation of the cell cycle by phosphorylating the nuclear envelope protein barrier-to-autointegration factor/BAF that is required for disassembly and reassembly, respectively, of the nuclear envelope during mitosis. Under normal physiological conditions, negatively regulates ERK activity along with VHR/DUSP3 phosphatase in the nucleus, causing timely and transient action of ERK. Stress conditions activate CDK5 which phosphorylates VRK3 to increase VHR phosphatase activity and suppress prolonged ERK activation that causes cell death. For example, upon glutamate induction, promotes nuclear localization of HSP70/HSPA1A to inhibit ERK activation via VHR/DUSP3 phosphatase.
Tractability: PROTAC: UniProt records ubiquitination sites on it; ubiquitination databases record sites on it; its protein half-life has been measured.
Gene: Protein-coding gene on chromosome 19 (49,976,127 to 50,025,946, reverse strand). Ensembl gene ENSG00000105053.
Subcellular location: Nucleus; Cytoplasm
Subcellular location (Human Protein Atlas): Nucleoplasm; Vesicles
Pathways (Reactome):
Signal Transduction: ERKs are inactivated
Gene Ontology:
Molecular function: protein binding; protein phosphatase binding; protein serine kinase activity; ATP binding; cyclin-dependent protein serine/threonine kinase activity; protein kinase activity; protein phosphatase activator activity
Biological process: skeletal muscle tissue development; DNA damage response; regulation of cell cycle
Cellular component: cytoplasm; nucleoplasm; nucleus
Genetic constraint (gnomAD): Loss-of-function variants: 50 observed, 63.08 expected, observed/expected ratio (o/e) 0.79, 90% interval 0.63 to 1. The upper end of that interval is the gene's LOEUF score, 1, which puts it in group 4 of 6, group 1 being the genes least tolerant of losing a copy. Missense variants: 549 observed, 612.04 expected, observed/expected ratio (o/e) 0.9, 90% interval 0.84 to 0.96. Synonymous variants: 246 observed, 239.7 expected, observed/expected ratio (o/e) 1.03, 90% interval 0.92 to 1.14.
Homologues: Orthologues: chimpanzee VRK3 (98% identical), macaque VRK3 (94% identical), pig VRK3 (73% identical), rat Vrk3 (72% identical), mouse Vrk3 (72% identical), guinea pig VRK3 (66% identical), dog VRK3 (62% identical), rabbit VRK3 (57% identical), tropical clawed frog vrk3 (39% identical), zebrafish vrk3 (38% identical), Drosophila melanogaster ball (19% identical), Caenorhabditis elegans C28A5.6 (18% identical), and 63 more. Paralogues in human: VRK2 (24% identical), VRK1 (24% identical), CSNK1G2 (16% identical), CSNK1G3 (16% identical), CSNK1E (15% identical), CSNK1A1 (15% identical), CSNK1D (15% identical), CSNK1G1 (15% identical), CSNK1A1L (15% identical), TTBK1 (12% identical), TTBK2 (12% identical), CDC7 (10% identical).
Diseases named in the same sentence as VRK3 in open-access papers:
VRK3 is named in the same sentence as 12 diseases in open-access papers, as found by Europe PMC text mining. Sharing a sentence is not in itself a finding about the gene and the disease. The quoted sentences say what the papers report.
Alzheimer disease (2 papers, 2016). A progressive, neurodegenerative disease characterized by loss of function and death of nerve cells in several areas of the brain leading to loss of cognitive function such as memory and language. "Importantly, we showed an association between phospho-VRK3 levels and the progression of human Alzheimer’s disease (AD) and Parkinson’s disease (PD)." (PMID 27346674, 2016). "Importantly, we showed a positive correlation between levels of VRK3 and HSP70 in the progression of Alzheimer’s and Parkinson’s diseases in humans, and neurons with HSP70 nuclear localization exhibited less Aβ accumulation in brains from patients with Alzheimer’s disease." (PMID 27941812, 2016).
glioma (2 papers, 2023 to 2026). A benign or malignant brain and spinal cord tumor that arises from glial cells (astrocytes, oligodendrocytes, ependymal cells). "These insights advance the understanding of phosphorylation control by kinases and highlight opportunities to target VRK3-associated networks for therapeutic intervention in diseases such as glioma and liver cancer." (PMID 41893729, 2026). "We observed that in adult glioma high VRK3 expression was correlated with decrease in overall survival independently of the grade of the tumor, whereas VRK2 expression was associated with an increase of survival in high-grade astrocytoma." (PMID 37886173, 2023). "It would thus be interesting to investigate if VRK3 depletion is also synthetic lethal in other pediatric tumor entities without hypermethylation of VRK2 promoter, and in particular posterior fossa type A ependymoma and infant high-grade glioma." (PMID 37886173, 2023).
liver cancer (2 papers, 2023 to 2026). An epithelial or non-epithelial malignant neoplasm that arises from the liver. "Another study in liver cancer reported a growth inhibition following VRK3 silencing but resulting from arrests in S and G2/M phases." (PMID 37886173, 2023). "Both VRK1 and VRK3 were shown to promote liver cancer progression, VRK1 regulating G1/S transition and mitosis and VRK3 S phase progression." (PMID 37886173, 2023).
autism (1 paper, 2023). Persistent deficits in social interaction and communication and interaction as well as a markedly restricted repertoire of activity and interest as well as repetitive patterns of behavior. "Moreover, TrkB activation by 7,8-DHF treatment restored social interactions in VRK3-deficient mice showing autism-like behavior (12–15 weeks old)." (PMID 37240625, 2023).
neuroblastoma (1 paper, 2016). Neuroblastoma (NB) is the most common solid, extracranial childhood tumor. "Taken together, these data indicated that VRK3 attenuates H2O2-induced apoptosis in neuroblastoma SH-SY5Y cells through suppression of prolonged ERK activation." (PMID 27346674, 2016). "We next determined the relevance of Ser 108 phosphorylation of VRK3 in H2O2-induced apoptosis of SH-SY5Y human neuroblastoma cells." (PMID 27346674, 2016). "Overexpression of VRK3 protected human neuroblastoma SH-SY5Y cells against hydrogen peroxide (H2O2)-induced apoptosis." (PMID 27346674, 2016).
cancer (2 papers, 2023 to 2024). A tumor composed of atypical neoplastic, often pleomorphic cells that invade other tissues. "Our analyses revealed that certain genes, such as PHF19 and VRK3, which are truncated in 9 and 5 different cancers, respectively, exhibit a negative correlation between the TR and disease-free survival time or survival rate in specific cancer types." (PMID 39349823, 2024).
neurodegenerative disease (2 papers, 2016). A disorder of the central nervous system characterized by gradual and progressive loss of neural tissue and neurologic function. "Therefore, HSP70 and VRK3 could potentially serve as diagnostic and therapeutic targets in neurodegenerative diseases." (PMID 27941812, 2016). "Together our work reveals endogenous protective mechanism against oxidative stress-induced neuronal cell death and suggest VRK3 as a potential therapeutic target in neurodegenerative diseases." (PMID 27346674, 2016). "It is likely that VRK3 has a protective role against oxidative stress in the early stages of neurodegenerative diseases." (PMID 27346674, 2016). "Therefore, HSP70 and VRK3 may be useful indicators for diagnosing the progressive stages of AD or PD and serve as therapeutic targets in neurodegenerative diseases." (PMID 27941812, 2016).
tumor (2 papers, 2022 to 2023). "In this context, it will also be pivotal to confirm the ability of VRK3 targeting to lead to tumor regression in vivo through the use of patient-derived xenograft models." (PMID 37886173, 2023). "VRK3 is involved in the cell cycle regulation, DNA repair, and neuronal differentiation of diffuse pontine gliomas, which are the essential genes for tumor cell survival." (PMID 35559251, 2022).
VRK3 also shares sentences with these, for which no sentence is quoted: Parkinson disease (2 papers); diabetes (1); diffuse midline glioma (1); ependymoma (1).